ANK1 (ankyrin 1)
Diseases named in the same sentence as ANK1 in open-access papers (continued):
Sharing a sentence is not in itself a finding about the gene and the disease.
autism (2 papers, 2017 to 2023). Persistent deficits in social interaction and communication and interaction as well as a markedly restricted repertoire of activity and interest as well as repetitive patterns of behavior. "Similarly, the correlation between Ank1 and FRmax is intriguing because Ank1, an isoform of the autism gene Ank3, helps coordinate the localization of Nav subunits to the nodes of Ranvier." (PMID 29069078, 2017).
cyst (2 papers, 2017 to 2021). A sac-like closed membranous structure that may be empty or contain fluid or amorphous material. "Surprisingly, inactivation of neither ANK1 nor DnaK-TPR seemed to have a significant impact on bradyzoite differentiation in vitro or cyst formation in vivo." (PMID 29180989, 2017). "Several other bradyzoite proteins whose expression increased included Ank1, a tetratricopeptide-repeat protein highly upregulated in the cyst-stages but not necessary for stage conversion, aspartyl protease ASP1, an α-galactosidase, as well as several dense granule proteins (GRA)." (PMID 34793583, 2021). "In this study when we knocked out either of the two TPR containing proteins (ANK1 and DnaK-TPR), no obvious phenotypes in bradyzoite conversion in vitro or cyst formation in vivo were observed, suggesting that they are not directly involved in chronic infection establishment." (PMID 29180989, 2017). "Possible reasons include: ANK1 and DnaK-TPR are not directly involved in cyst establishment, but may play roles in the structure integrity or physiological fitness of the cysts, which are not caught in our tests due to limited sensitivity." (PMID 29180989, 2017).
Hyperbilirubinemia (2 papers, 2013 to 2015). An increased amount of bilirubin in the blood. "Mild hyperbilirubinemia were observed in the proband (II.2) and his mother (I.2), related to the presence of the p.Q1772X ANK1 mutation." (PMID 26107955, 2015). "Thus, layered on a homozygous p.G71R UGT1A1 background, the additional ANK1 mutation appeared to cause hyperbilirubinemia." (PMID 26107955, 2015).
iron overload (2 papers, 2020 to 2022). "Specifically, the mutation of the SNP rs516946 in the ANK1 gene has been identified as being associated with iron overload, which plays a role in the progression of T2DM, and, thus, the site is regarded as a T2DM-susceptibility locus." (PMID 35631165, 2022). "Similarly, a frameshift mutation of ANK1 has been found in patients with body iron overload." (PMID 35631165, 2022).
leukaemia (2 papers, 2017 to 2022). "The ANK1 variant 1–4, observed to be co-expressed with miR-486-5p in our study, has previously been shown to be relevant for miR-486-5p expression in leukaemia." (PMID 35172717, 2022). "Using RNA sequencing, we found that genes associated with AML subtypes, such as RYR3, RHAG, PCDH9, ANK1, ADAMTS3, and DLC1, were significantly up-regulated in the leukemia cells of two responders, but not in the 3 non-responders." (PMID 28900115, 2017).
melanoma (2 papers, 2019 to 2022). A malignant, usually aggressive tumor composed of atypical, neoplastic melanocytes. "We show that ANK-1+ CD56dim CD16− NK cells are underrepresented within melanoma lesions as compared to circulation, likely indicating altered cytolytic state of CD56dim CD16− TINKs." (PMID 30761123, 2019).
metabolic syndrome (2 papers, 2022 to 2023). A cluster of metabolic risk factors for CARDIOVASCULAR DISEASES and TYPE 2 DIABETES MELLITUS. "This study aimed to explore the role of the single nucleotide polymorphism (SNP) rs516946 of the Ankyrin 1 (ANK1) gene in the relationship between dietary iron and metabolic syndrome (MetS) in the Chinese population." (PMID 35631165, 2022). "While previous reports have shown elevation in haptoglobin (HPT) in individuals with elevated glucose and metabolic syndrome, alterations in ANK-1 do not appear to have been reported previously." (PMID 36902363, 2023).
Obesity (2 papers, 2023 to 2025). Accumulation of substantial excess body fat. "Our data suggest that epigenetic changes in ANK1 may represent a potential link between maternal obesity and subsequent childhood NAFLD; alternatively, this association may be driven by obesity acting on differential DNA methylation and subsequently influencing NAFLD in adolescence." (PMID 36737504, 2023).
thalassemia (2 papers, 2021 to 2024). An inherited blood disorder characterized by a decreased synthesis of one of the polypeptide chains that form hemoglobin. "In our study, we found overexpression of the genes SLC4A1, ANK1, EPB41, EPB42, SPTA1, SPTB, and STOM, all of which are involved in maintaining erythrocyte structure and function, in patients with thalassemia and SCD." (PMID 39519257, 2024).
acute myeloid leukemia (1 paper, 2022). Acute myeloid leukemia (AML) is a group of neoplasms arising from precursor cells committed to the myeloid cell-line differentiation. "ANK1 participates in the malignant progression of acute myeloid leukemia in the elderly and in children with Down syndrome, related to erythropoietin, which provides a potential molecular link for MM secondary acute myeloid leukemia and mediating poor prognosis." (PMID 36131282, 2022).
asthma (1 paper, 2025). "Transient receptor potential channels, specifically vanilloid receptor 1 (TRPV1) and ankyrin 1 (TRPA1), are polymodal sensory channels extensively distributed in the lungs and represent promising therapeutic targets for asthma." (PMID 40678720, 2025).
autism spectrum disorder (1 paper, 2023). A spectrum of developmental disorders that includes autism, and Asperger syndrome. "The LoF variant in ANK1 causes haploinsufficiency and results in autism spectrum disorder." (PMID 36875658, 2023).
cardiac arrhythmia (1 paper, 2024). Any disturbances of the normal rhythmic beating of the heart or MYOCARDIAL CONTRACTION. "Combined with the existing studies, Ank1 disorders were found to be closely associated with cardiac arrhythmias, and the pathological mechanism is that mutations in Ank1 result in subsequent disorganization or mislocalization of ion channels and membrane transport proteins." (PMID 39456238, 2024).
cerebral amyloid angiopathy (1 paper, 2019). "ANK1 binds to the erythrocyte membrane protein band 4.2 (EPB42, present in this module) to vimentin which is implicated in neuroinflammation and in cerebral amyloid angiopathy, which is one of the major causes of ICH." (PMID 30836997, 2019).
cerebral malaria (1 paper, 2018). A sequestration of Plasmodium falciparum in the brain, which can cause coma and/or seizures. "The five identified proteins (ANK1, CD14, CDK14, ELANE, MPP1) were found to be elevated in the febrile convulsion group compared to cerebral malaria." (PMID 30442134, 2018).
cholelithiasis (1 paper, 2025). The presence of crystallized deposits forming in the gallbladder or biliary tree, primarily composed of cholesterol, bilirubin, and bile. "In addition, ANK1-HS also presented more cholelithiasis and elevated bilirubin levels." (PMID 39995895, 2025).
chronic lymphocytic leukemia (1 paper, 2020).
colorectal cancer (1 paper, 2022). A primary or metastatic malignant neoplasm that affects the colon or rectum. "Subclonal ANK1 mutation-drive genes show positive associations with infiltration levels of Treg cells and myeloid derived suppressor cells, which may cause tumor immune escape thus contributing to a poor outcome in colorectal cancer." (PMID 35962343, 2022).
COVID-19 (1 paper, 2024). A disease caused by infection with severe acute respiratory syndrome coronavirus 2. "Immunological cross-reactivity between ankyrin 1 (ANK-1), an RBC membrane protein, and spike proteins in a virus has been implicated in the pathogenesis of AIHA among patients with COVID-19." (PMID 38360719, 2024).
epilepsy (1 paper, 2017). A brain disorder characterized by episodes of abnormally increased neuronal discharge resulting in transient episodes of sensory or motor neurological dysfunction, or psychic dysfunction. "Considering that KCNQ2 and KCNQ3 turned out to directly contributing to the initiation and progression of epilepsy, our predicted genes ANK1 and ANK2 as the functional components of ankyrins may very probably be epilepsy associated genes, validating our prediction." (PMID 28255556, 2017).
hereditary elliptocytosis (1 paper, 2021). Hereditary elliptocytosis (HE) is a rare clinically and genetically heterogeneous disorder of the red cell membrane characterized by manifestations ranging from mild to severe transfusion-dependent hemolytic anemia but with the majority of patients being asymptomatic. "Unlike ANK1 mutations, which were identified only in HS patients, SPTB mutations could result in other diseases including hereditary elliptocytosis and hereditary pyropoikilocytosis." (PMID 34335240, 2021).
Leukoencephalopathy (1 paper, 2025). This term describes abnormality of the white matter of the cerebrum resulting from damage to the myelin sheaths of nerve cells. "Several genome-wide association studies (GWAS) have identified single-nucleotide polymorphisms (SNPs) in the following genes: TRIO, PRKG1, ANK1, COL4A2, NTN1, and ASTN2 that were associated with increased risk of MTX-induced neurotoxicity and leukoencephalopathy on imaging in patients with ALL." (PMID 41029358, 2025).
lung adenocarcinoma (1 paper, 2016). A carcinoma that arises from the lung and is characterized by the presence of malignant glandular epithelial cells. "Of the 16 distinguishing proteins, 8 were significantly elevated in lung adenocarcinoma (COPG1, STOML2, HYOU1, PDIA4, EPRS, APEX1, LRPPRC and NANS) whereas 8 proteins were significantly decreased in lung adenocarcinoma (SPTB, SPTA1, ANK1, SLC4A1, HBG1 and HBG2)." (PMID 27799870, 2016).
metastatic cancer (1 paper, 2016). A carcinoma which has spread from the original site of growth to another anatomic site. "Adenocarcinoma-associated reductions in spectrins, SPTB and SPTA1, and ankrin (ANK1) all interact with each another to regulate cell shape and membrane integrity, so paralleled changes likely reflect changes in cell adherence, which is a known hallmark of metastatic cancer." (PMID 27799870, 2016).
migraine (1 paper, 2022). "In particular, the subtypes ankyrin 1 (TRPA1) and vanilloid 1 (TRPV1) are activated by migraine provoking agents." (PMID 35350752, 2022).
myeloid leukaemia (1 paper, 2022). "In myeloid leukaemia with an erythroid phenotype, miR-486-5p was regulated through GATA1 binding to the promoter region of ANK1 variant 1–4." (PMID 35172717, 2022).
neuroblastoma (1 paper, 2022). Neuroblastoma (NB) is the most common solid, extracranial childhood tumor. "In this study, we differentiated neuroblastoma cells into a neuronal-like phenotype with retinoic acid and studied if functional acid-sensing, transient receptor potential vanilloid-1 and ankyrin-1 ion channels were expressed in it." (PMID 35205034, 2022). "We investigated acid-sensing (ASIC) and transient receptor potential vanilloid-1 (TRPV1) and ankyrin-1 (TRPA1) ion channels present in untreated and differentiated neuroblastoma SH-SY5Y to propose a new means for their study in neuronal-like cells." (PMID 35205034, 2022). "In the present research, we examined RA-treated human neuroblastoma SH-SY5Y in comparison with its untreated counterpart as a prospective in vitro model system to study native acid-sensing, transient receptor potential vanilloid-1 (TRPV1) and ankyrin-1 (TRPA1) ion channels." (PMID 35205034, 2022).
non-alcoholic steatohepatitis (1 paper, 2023). "ANK1 protein is found in circulating extra-cellular vesicles in animal models of non-alcoholic steatohepatitis (NASH), suggesting a role in cell-to-cell signaling." (PMID 36737504, 2023).
oral cancer (1 paper, 2019). "Further clinical analysis showed that the methylation index (AVG Beta) of ANK1 was significantly higher in oral cancer tissues compared with the normal control in our methylation array data (GSE38823)." (PMID 31253192, 2019). "In this study, we found that arecoline treatment could recruit DNMT3B to ANK1 promoter and suppresses ANK1 and miR-486-3p expression, subsequently upregulated expression of DDR1 in oral cancer." (PMID 31253192, 2019).
osteoarthritis (1 paper, 2023). A noninflammatory degenerative joint disease occurring chiefly in older persons, characterized by degeneration of the articular cartilage, hypertrophy of bone at the margins and changes in the synovial membrane. "Thus, the effect of allyl isothiocyanate on chondrocytes is conditionally controllable, which could be associated with transient receptor potential ankyrin 1 activation, and is a promising strategy for osteoarthritis treatment." (PMID 37006615, 2023).
pancreatic adenocarcinoma (1 paper, 2016). "In summary, we find that ANK1 is overexpressed in the majority of pancreatic adenocarcinomas in association with DNA hypomethylation and promotes growth in soft agar and tumor growth in vivo." (PMID 27144336, 2016). "We examined the expression and transcriptional regulation of ANK1 in pancreatic adenocarcinomas and investigated its potential role in tumor progression." (PMID 27144336, 2016). "Next, we performed immunohistochemical labeling of ankyrin-1 on TMAs containing primary pancreatic adenocarcinomas and adjacent non-neoplastic pancreatic tissues." (PMID 27144336, 2016).
parasite (1 paper, 2013). "In nb/nb and Ank1MRI23420 mice, it is difficult to evaluate the involvement of wild-type ankyrin-1 in the parasite infection because of the existence of truncated ankyrin proteins." (PMID 23934996, 2013).
periodontitis (1 paper, 2024). An acute or chronic inflammatory process that affects the tissues that surround and support the teeth. "In addition, specific biological processes and molecular functions during progressive periodontitis were revealed and a set of hub proteins, including SNCA, CA1, HBB, SLC4A1, and ANK1 was strongly associated with the clinical progression status of periodontitis." (PMID 38802345, 2024). "Herein, SNCA, CA1, HBB, SLC4A1, and ANK1, were identified as hub proteins of periodontitis progression." (PMID 38802345, 2024). "In this study, SNCA, CA1, SLC4A1, ANK1, and HBB were identified as hub proteins associated with periodontitis progression." (PMID 38802345, 2024).
protein deficiency (1 paper, 2023). "Previous research has shown that erythrocyte membrane protein deficiency caused by pathogenic mutations in the ANK1, SLC4A1, SPTA1, SPTB, and EPB42 genes is the molecular pathogenesis of HS." (PMID 36647015, 2023).
Salmonella Infections (1 paper, 2013). Infections with bacteria of the genus SALMONELLA. "The critical role of HAMP in the host response to Salmonella infection was validated by showing increased susceptibility to infection in Hamp-deficient mice and significant survival benefits in Ank1+/Ity16 heterozygous mice treated with HAMP peptide." (PMID 23390527, 2013). "Overall, the current study shows that the suppression of Hamp expression and iron overload contribute to the susceptibility of Ank1Ity16/Ity16 mutant and Ank1+/Ity16 heterozygous mice to Salmonella infection." (PMID 23390527, 2013). "This study illustrates that the regulation of Hamp and iron balance are crucial in the host response to Salmonella infection in Ank1 mutants." (PMID 23390527, 2013). "Ank1+/Ity16 heterozygous mice treated with HAMP peptide showed significant survival benefits (Log Rank (Mantel-Cox) test p = 0.008) compared to heterozygous mice treated with PBS confirming the importance of HAMP in the host response to Salmonella infection." (PMID 23390527, 2013). "Finally, direct evidence of the role of Hamp in the host response to Salmonella infection was obtained by treating Ank1+/Ity16 mice with hepcidin." (PMID 23390527, 2013).
squamous cell carcinoma (1 paper, 2018). A carcinoma arising from squamous epithelial cells. "ANK1 methylation is significantly more prevalent in adenocarcinoma compared to squamous cell carcinoma." (PMID 29723992, 2018). "The ANK1 promoter CpG island is unmethylated in normal lungs, but is methylated in the lungs of individuals with adenocarcinoma, and more so than in those with squamous cell carcinoma." (PMID 29723992, 2018).
steatosis (1 paper, 2023). Increased lipid within the cytoplasm of cells. "Using pyrosequencing, associations in one of these genes (ANK1) were confirmed with both steatosis score and NAFLD after accounting for waist circumference and cell count heterogeneity." (PMID 36737504, 2023). "We identified dmCpGs in three genes (ANK1, MIR10A, PTPRN2) that were associated with steatosis score." (PMID 36737504, 2023).
tauopathy (1 paper, 2020). Neurodegenerative disorders involving deposition of abnormal tau protein isoforms (tau proteins) in neurons and glial cells in the brain. "Research shows that Aβ, tauopathy, and mutations of genes contributing to AD, e.g., Ankyrin 1 gene increase neurodegeneration, disrupt memory, decrease locomotion, and shorten lifespan in Drosophila." (PMID 33003559, 2020).
Thrombocytosis (1 paper, 2013). Increased numbers of platelets in the peripheral blood. "The Ank1EX34 pedigree also exhibited thrombocytosis, a characteristic not commonly associated with Ank1 mutation or HS." (PMID 24688720, 2013).